ADGRF3 (adhesion G protein-coupled receptor F3)
Description:
Orphan receptor.
Synonyms: GPR113; PGR23; hGPCR37
Tractability: Antibody: UniProt predicts a signal peptide or a membrane-spanning region.
Target class: Family B G protein-coupled receptor; Membrane receptor
Gene: Protein-coding gene on chromosome 2 (26,308,173 to 26,346,817, reverse strand). Ensembl gene ENSG00000173567.
Subcellular location: Membrane
Subcellular location (Human Protein Atlas): Golgi apparatus; Cytosol
Gene Ontology:
Molecular function: G protein-coupled receptor activity; transmembrane signaling receptor activity
Biological process: adenylate cyclase-activating G protein-coupled receptor signaling pathway; G protein-coupled receptor signaling pathway; cell surface receptor signaling pathway
Cellular component: membrane; plasma membrane
Genetic constraint (gnomAD): Loss-of-function variants: 85 observed, 95.19 expected, observed/expected ratio (o/e) 0.89, 90% interval 0.75 to 1.07. The upper end of that interval is the gene's LOEUF score, 1.07, which puts it in group 4 of 6, group 1 being the genes least tolerant of losing a copy. Missense variants: 1,125 observed, 1,280.6 expected, observed/expected ratio (o/e) 0.88, 90% interval 0.84 to 0.92. Synonymous variants: 534 observed, 553.54 expected, observed/expected ratio (o/e) 0.96, 90% interval 0.9 to 1.04.
Homologues: Orthologues: chimpanzee ADGRF3 (94% identical), macaque ADGRF3 (91% identical), pig ADGRF3 (71% identical), dog ADGRF3 (71% identical), rabbit ADGRF3 (66% identical), guinea pig ADGRF3 (61% identical), mouse Adgrf3 (60% identical), rat Adgrf3 (59% identical). Paralogues in human: ADGRF5 (26% identical), ADGRF1 (20% identical), ADGRF4 (17% identical), ADGRL2 (16% identical), ADGRL3 (16% identical), ADGRG4 (16% identical), ADGRL1 (16% identical), ADGRG6 (15% identical), ADGRE2 (15% identical), ADGRE5 (15% identical), ADGRD2 (15% identical), ADGRB1 (14% identical), and 30 more.
Diseases named in the same sentence as ADGRF3 in open-access papers:
ADGRF3 is named in the same sentence as 3 diseases in open-access papers, as found by Europe PMC text mining. Sharing a sentence is not in itself a finding about the gene and the disease.
ADGRF3 shares sentences with these, for which no sentence is quoted: congenital heart defects (1 paper); endometriosis (1); neurodevelopmental disorder (1).